RNU2-43P (RNA, U2 small nuclear 43, pseudogene)
Gene: Small nuclear RNA gene on chromosome 10 (101,307,529 to 101,307,718, forward strand). Ensembl gene ENSG00000222238.
Homologues: Orthologues: chimpanzee U2 (99% identical), macaque U2 (94% identical). Paralogues in human: U2 (83% identical), U2 (82% identical), RNU2-2 (82% identical), RNU2-3P (82% identical), RNU2-14P (81% identical), RNU2-59P (81% identical), RNU2-39P (81% identical), RNU2-32P (79% identical), RNU2-4P (79% identical), RNU2-61P (79% identical), RNU2-64P (79% identical), RNU2-6P (79% identical), and 66 more.